MIR1976 (microRNA 1976)
Synonyms: hsa-mir-1976
Gene: MicroRNA gene on chromosome 1 (26,554,542 to 26,554,593, forward strand). Ensembl gene ENSG00000238705.
Homologues: Orthologues: chimpanzee MIR1976 (100% identical).